IGF2BP2 (insulin like growth factor 2 mRNA binding protein 2)
Diseases named in the same sentence as IGF2BP2 in open-access papers (continued):
Sharing a sentence is not in itself a finding about the gene and the disease.
tumor (continued). "Moreover, METTL3 or IGF2BP2 expression positively correlated with the SOX2 downstream genes CCND1, MYC, and POU5F1 in our independent cohort of paired CRC tumor and adjacent normal tissues from SYSUCC." (PMID 31230592, 2019). "Other candidate tumour suppressors, such as MAFTRR, KIAA1551, and IGF2BP2, are novel." (PMID 29089486, 2017). "Moreover, we observed a trend where tumor tissues with distal metastasis exhibited higher IGF2BP2 expression compared to those without metastasis." (PMID 40084251, 2025). "How IGF2BP2 regulates TFRC may be a watershed event in iron metabolism and tumor progression." (PMID 37088822, 2023). "Furthermore, Western blotting and IHC assay also verified the downregulation of IGF2BP2 protein in ccRCC tumour tissues compared with matched adjacent noncancerous tissues." (PMID 35876041, 2022). "Circ_0001756 could bind and positively regulate IGF2BP2 and RAB5A to activate the downstream EGFR/MAPK signaling pathway, thereby inducing cell proliferation, invasion, and epithelial-mesenchymal transition (EMT) in vitro and tumor growth in vivo." (PMID 36428803, 2022). "Functional researches showed that IGF2BP2 knockdown inhibited viability, proliferation, accelerates apoptosis of crizotinib-resistant A549 and H1299 cells, and inhibited crizotinib-resistant NSCLC tumor growth, indicating that IGF2BP2 knockdown alleviates crizotinib-resistant NSCLC progression." (PMID 34630126, 2021). "Therefore, we performed RT‐qPCR assays to identify target mRNAs that were regulated by both PCAT6 and IGF2BP2 in these tumor‐related mRNAs and found that IGF1R was the most downregulated mRNA both in PCAT6‐ and IGF2BP2‐knockdown PC‐3 cells compared with control PC‐3 cells." (PMID 34185427, 2021). "Although high expression of IGF2BP2 was not a strong indicator of prognosis, leukocyte subsets analyses indicated that it was significantly negatively correlated with the infiltration of tumor infiltrating lymphocytes (TILs)." (PMID 33500720, 2021). "In addition, 43 matched tumor tissues and their corresponding noncancerous tissues indicated higher IGF2BP2 expression in the tumors (p < 0.001)." (PMID 32784624, 2020). "Knockdown the IGF2BP2 expression reduced tumor growth, as evidenced by the higher tumor volume and tumor weight; IGF2BP2 expression could not be detected in tumor tissues of IGF2BP2 knockdown mice." (PMID 33224879, 2020). "Furthermore, miR-216b downregulated the expression of insulin-like growth factor 2 mRNA-binding protein 2 (IGF2BP2) and exerted its tumor-suppressor function through inhibition of protein kinase B and extracellular signal-regulated kinase signaling downstream of IGF2." (PMID 25741595, 2015). "However, the function and expression of IGF2BP2 are not consistent in different tumours." (PMID 35876041, 2022). "Hence, the results revealed that the high-risk score may be an essential factor for B and T cell growth and differentiation leading to tumor immunosuppression, and the low expression of EZH2 and AZGP1 and high expression of IGF2BP2 were the main factors of tumor immunosuppression in the risk model." (PMID 33505420, 2020). "Although not yet tested in CRC, the IGF2BP2 and IGF2BP3 inhibitors effectively inhibited tumor growth in model organisms and cancer cell lines." (PMID 39456596, 2024). "For example, lncRNA LINRIS can affect tumor glycolysis by stabilizing the IGF2BP2 protein, but there is no co-expression relationship between LINRIS and IGF2BP2 at the RNA level." (PMID 34527595, 2021). "We evaluated the tumor growth patterns of 174 PDX models that were not subjected to any drug treatment and classified them into two groups based on the expression patterns of PLK1 and IGF2BP2." (PMID 40347943, 2025). "Based on TCGA database, we discovered that expressions of IGF2BP2 and IGF2BP3 were significantly upregulated in ESCA tissues compared with normal tissues, and the expressions of the other 12 RBPs were not altered in tumor tissues versus normal tissues." (PMID 32239639, 2020).
tumor (continued). "Albeit the roles of AZGP1 and IGF2BP2 in the immune response have not been investigated, our study was first to suggest that AZGP1 downregulation and IGF2BP2 upregulation may act as suppressors in tumor immune response in SCCHN." (PMID 33505420, 2020).
cancer (224 papers, 2009 to 2026). A tumor composed of atypical neoplastic, often pleomorphic cells that invade other tissues. "Several case-control studies investigated associations between IGF2BP2 polymorphisms and cancer progression." (PMID 40084251, 2025). "Studies have shown that IGF2BP2 dysregulation is associated with various diseases, including cancer, diabetes, and insulin resistance." (PMID 39948708, 2025). "Both Spon2 and IGF2BP2 have been implicated in the progression and metastasis of human cancers, including LC." (PMID 39731162, 2024). "Insulin-like growth factor 2 mRNA-binding protein 2 (IGF2BP2) is associated with a worse prognosis in patients with OSCC by regulating cancer-related biological pathways, such as glycolysis, epithelial-mesenchymal transition, and the cell cycle." (PMID 39511483, 2024). "IGF2BP2 is an RNA-binding proteins that is involved in regulating multiple biological processes and associated with a variety of diseases and cancers." (PMID 38782769, 2024). "A comprehensive pan-cancer analysis has demonstrated that elevated expression levels of IGF2BP2 are associated with poor prognosis across various cancer types." (PMID 39596216, 2024). "IGF2BP2 has been proven to play an oncogenic role and its expression is associated with poor prognosis in various cancers." (PMID 38042777, 2023). "Through KEGG enrichment analysis, we observed a significant association between elevated IGF2BP2 expression and microRNAs in cancer." (PMID 37936610, 2023). "In this study, we showed that IGF2BP2 was highly expressed in carcinoma-associated MSCs and played a crucial role in reprogramming MSCs." (PMID 37865637, 2023). "Previous studies have shown that dysregulation of IGF2BP2 is associated with the growth, migration, adhesion, and energy metabolism of cancer cells, and it modulates the occurrence and development of many human diseases such as diabetes and malignant tumors." (PMID 35129592, 2022). "IGF2BP2 has been shown to be overexpressed in many cancers and associated with poor patient survival." (PMID 35717493, 2022). "A number of studies have linked IGF2BP2 gene polymorphisms to the incidence of type 2 diabetes and cancer 17-20." (PMID 35919812, 2022). "In GEPIA2, we found the higher IGF2BP2 expression was significantly associated with poor prognosis of most cancers, such as BLCA, GBM, HNSC, KIRC, LGG, LUAD, PAAD, SARC." (PMID 36281789, 2022). "We also summarized current works on the association among IGF2BP2, miRNAs, lncRNAs, mRNAs and other m6A-related genes and development as well as regulation of cancers." (PMID 33568150, 2021). "In this review, we summarize the current evidence on the relationship between IGF2BP2 and metabolic disease, as well as the biological mechanisms underlying IGF2BP2 functions in cancers." (PMID 33568150, 2021). "Previous studies have shown that IGF2BP2 expression is increased in several types of carcinomas, and that it is associated with cancer cell proliferation, migration, adhesion and energy metabolism." (PMID 34608837, 2021). "In particular, upregulation of the IGF2BP2 gene was associated with poor patient survival in seven cancer types, including HNSCC." (PMID 33816266, 2021). "In recent years, over-expression of IGF2BP2 in multiple human cancers has been associated with poorer prognosis of the disease." (PMID 33568150, 2021). "Studies have reported that IGF2BP2 is amplified and overexpressed in numerous cancers and is often associated with poor prognosis." (PMID 32784624, 2020). "Several case–control studies have reported that IGF2BP2 rs4402960 is associated with cancer progression." (PMID 32784624, 2020). "Dysregulation of IGF2BP2 is often associated with human diseases such as insulin resistance, diabetes, or cancer." (PMID 31804607, 2020). "This review summarizes the structural features, regulation, and functions of IGF2BP2 and their association with cancer and cancer stem cells." (PMID 29736175, 2018).
cancer (continued). "Here, to clarify the genetic association between IGF2BP2 and EC development, genotyping of three single-nucleotide polymorphisms (SNPs) of IGF2BP2 gene, including rs11705701, rs4402960, and rs1470579, were conducted in 190 patients and 295 cancer-free women." (PMID 42158820, 2026). "IGF2BP2, a well-characterized m6A reader and oncogenic mRNA stabilizer, has repeatedly been associated with proliferation and poor survival outcomes in various cancers including HNSC." (PMID 40565233, 2025). "IGF2BP2 has been implicated in the stabilization of mRNAs involved in critical cellular processes such as growth, differentiation, and metabolism, which are essential for cancer progression." (PMID 40697388, 2025). "To determine whether known targets of LIN28A/LIN28B would be able to rescue cancer initiation in Lin28a/Lin28b-deficient mice, we tested Igf2bp1, Igf2bp2, and Igf2bp3." (PMID 38875287, 2024). "Dysregulation of IGF2BP2 has been linked to various metabolic diseases and cancers." (PMID 39659616, 2024). "The upregulation of IGF2BP2 is associated with poor prognosis in various human cancers." (PMID 37865637, 2023). "Finally, in pan-cancer analysis, IGF2BP2 was up-regulated in most cancers and its overexpression was associated with poorer prognosis of cancer patients." (PMID 36281789, 2022). "IGF2BP2 has been implicated in a wide range of cancer types." (PMID 35915142, 2022). "Abnormal expression of IGF2BP2 is commonly linked to multiple diseases, including cancers." (PMID 34980207, 2022). "In addition, dysregulation of IGF2BP2 is associated with progression of cancers and cancer stem cells." (PMID 33568150, 2021). "On the other hand, over-expression of IGF2BP2 increases the risk of developing numerous cancers." (PMID 33568150, 2021). "IGF2BP2 can function as a post-transcriptional regulator of mRNA localization, stability and translation, and its dysregulated expression is usually associated with various types of cancer, such as colorectal, breast, pancreatic and non-small cell lung cancer." (PMID 34608837, 2021). "IGF2BP2 has been identified to be implicated in the malignant phenotype of cancer cells." (PMID 35173610, 2021). "Dysregulated IGF2BP2 could also affect the associated downstream genes via the m6A modification to accelerate cancer progression." (PMID 33816266, 2021). "We found that HNSCC has the lowest IGF2BP2 mutation frequency among multiple cancer types." (PMID 33816266, 2021). "The mutation frequency of the IGF2BP2 gene in each TCGA cancer type is shown as a bar plot." (PMID 33816266, 2021). "In addition, IGF2BP2 has been implicated in promoting cancer progression, including CRC." (PMID 41399129, 2025). "Moreover, recent studies indicated that the IGF2BP2 rs1470579 variant might play essential roles in diverse multifactorial diseases, including human metabolic disorders and cancers." (PMID 38468402, 2024). "Therefore, IGF2BP2 gene mutations may have a weak relationship with immune cell infiltration across 22 multiple cancer types and immune cell types." (PMID 33816266, 2021). "However, emerging evidence indicates that IGF2BP2 plays a role in cancer, but the underlying mechanism is largely unknown." (PMID 31804607, 2020). "Given that cancer progression involves gradual dedifferentiation and acquisition of stem cell-like properties(32, we next evaluated the impact of IGF2BP2 manipulation on differentiation marker expression." (PMID 41522349, 2026). "Functioning as an oncogenic driver, IGF2BP2 overexpression is prevalent across multiple cancer types, where it fuels pivotal cancer hallmarks." (PMID 41522349, 2026). "This aligns with a pan-cancer landscape bioinformatics analysis showing elevated IGF2BP2 expression in HNSCC, suggesting its potential as a robust therapeutic target." (PMID 40362183, 2025). "Igf2bp2 modulates cancer cell proliferation, migration, invasion, metastasis, and apoptosis by regulating the transcription of miRNAs, lncRNAs, and other m6A-related genes." (PMID 40182023, 2025).
cancer (continued). "While several studies explored the clinical significance of IGF2BP2 SNPs in various cancer types, their impacts on PCa remain unexplored." (PMID 40084251, 2025). "Notable downregulated genes included Mki67, Ccn1, Muc1, Atf3, Ntrk2, Arid5b, Igf1r, Igf2bp2, Cd47, and Cd37 (oncogenic function) and integrin-related genes, Itga7, Itga11, Itgam and Notch1 (cancer stem cell markers)." (PMID 39946195, 2025). "Emerging evidence reveals that IGF2BP2 participates in the development and progression of cancers by communicating with different RNAs, such as (miRNAs), lncRNAs, and circRNAs." (PMID 39969065, 2025). "By combining comprehensive genome-wide screening with in-depth validation, our study highlights IGF2BP2 as a compelling candidate for targeted therapy in PLK1-overexpressing cancers." (PMID 40347943, 2025). "Overall, these in vitro analyses support the potential for IGF2BP2 inhibition in the selective elimination of PLK1-overexpressing cancer cells." (PMID 40347943, 2025). "Consistent with this, pharmacological inhibition of IGF2BP2 severely impacts the viability of PLK1-overexpressing cancer cells addicted to higher metabolic rates." (PMID 40347943, 2025). "In our study, we identified five co-dysregulated RBPs, among which IGF2BP2 exhibited the most pronounced expression variability and the highest expression levels in both cancer cells and CAFs." (PMID 40362183, 2025). "Both mechanisms are potentially operative in most cancer cells, where IGF2BP2 inhibition decreases PLK1 expression." (PMID 40347943, 2025). "All human IGF2BPs have been determined as oncofetal proteins, and IGF2BP2, which can promote carcinogenesis by modulating cancer metabolism, is a distinct member of the IGF2BP family." (PMID 40936698, 2025). "While lower concentrations of C4 and C9 compounds suppressed PLK1 overexpressing cancer cells more effectively, compound C4 showed the best in vivo pharmacokinetic (PK) profile of the tested IGF2BP2 inhibitors." (PMID 40347943, 2025). "The data analyses revealed that 4132 genes were bound by IGF2BP2 and were enriched in several cancer pathways, including the MAPK pathway, Wnt pathway, Hippo pathway, and Notch pathway." (PMID 40629911, 2025). "These compounds demonstrated target-specific activity and promising anti-proliferative effects, establishing a framework for developing optimized IGF2BP2 inhibitors with enhanced potency and selectivity against IGF2BP2-driven cancers." (PMID 40823087, 2025). "The therapeutic potential of IGF2BP2 has recently gained attention, with specific inhibitors showing promise in suppressing cancer progression." (PMID 40507253, 2025). "IGF2BP2 is also an RNA-binding protein or “reader” that has been studied in cancers such as glioma, ovarian, prostate, pancreatic, breast, and many more." (PMID 40243425, 2025). "High expression of IGF2BP2 stabilizes m6A‐modified PD‐L1 mRNA, which increases PD‐L1 expression and promotes cancer growth." (PMID 40448344, 2025). "IGF2BP2 was the most markedly upregulated RBP in OSCC cells and cancer-associated fibroblasts (CAFs), correlating with unfavorable prognosis." (PMID 40362183, 2025). "Mechanistically, IGF2BP2 was shown to govern cancer metabolism, apoptosis, invasion, and metastasis by regulating different types of RNA species post-transcriptionally in numerous cell types and pathways." (PMID 38250159, 2024). "While circHIPK3 is frequently downregulated in cancer and positively correlated to good clinical outcomes, IGF2BP2 enhances genomic instability, is upregulated in cancer, and involved in cancer progression." (PMID 39041323, 2024). "A review of previous studies reveals that, while some research has shown IGF2BP2’s ability to inhibit cancer progression, the majority of evidence supports its role in promoting cancer." (PMID 39596216, 2024). "In HNSCC, IGF2BP2 has emerged as a key oncogene driven by oncogenic super-enhancers (SEs), which maintain its overexpression and cancer progression." (PMID 39596216, 2024).